MRPL33 (mitochondrial ribosomal protein L33)
Synonyms: L33mt; MRP-L33; C2orf1; RPL33L; bL33m
Tractability: Small molecule: a structure with a bound ligand is known. PROTAC: its protein half-life has been measured.
Gene: Protein-coding gene on chromosome 2 (27,771,717 to 27,988,087, forward strand). Ensembl gene ENSG00000243147.
Subcellular location: Mitochondrion
Pathways (Reactome):
Metabolism of proteins: Mitochondrial ribosome-associated quality control; Mitochondrial translation elongation; Mitochondrial translation initiation; Mitochondrial translation termination
Gene Ontology:
Molecular function: structural constituent of ribosome
Biological process: mitochondrial translation; translation
Cellular component: mitochondrial large ribosomal subunit; mitochondrion; mitochondrial inner membrane; cytoplasm; ribosome
Genetic constraint (gnomAD): Loss-of-function variants: 4 observed, 8.06 expected, observed/expected ratio (o/e) 0.5, 90% interval 0.24 to 1.13. That is too few expected variants to judge how well the gene tolerates losing a copy. Missense variants: 70 observed, 75.4 expected, observed/expected ratio (o/e) 0.93, 90% interval 0.76 to 1.13. Synonymous variants: 23 observed, 27.27 expected, observed/expected ratio (o/e) 0.84, 90% interval 0.61 to 1.2.
Homologues: Orthologues: chimpanzee MRPL33 (100% identical), pig MRPL33 (85% identical), rabbit MRPL33 (85% identical), rat Mrpl33 (78% identical), mouse Mrpl33 (77% identical), guinea pig MRPL33 (75% identical), zebrafish mrpl33 (68% identical).
Diseases named in the same sentence as MRPL33 in open-access papers:
MRPL33 is named in the same sentence as 21 diseases in open-access papers, as found by Europe PMC text mining. Sharing a sentence is not in itself a finding about the gene and the disease. The quoted sentences say what the papers report.
colorectal cancer (2 papers, 2025). A primary or metastatic malignant neoplasm that affects the colon or rectum. "For example, MRPL33 and its splicing regulator play a crucial role in colorectal cancer cells by promoting their growth and proliferation while inhibiting apoptosis." (PMID 40918472, 2025). "Additionally, MRPL33 promotes colorectal cancer cell proliferation and inhibits apoptosis, while its reduced expression induces mitochondrial dysfunction and enhances tumor cell apoptosis." (PMID 40713706, 2025).
acute myeloid leukemia (1 paper, 2020). Acute myeloid leukemia (AML) is a group of neoplasms arising from precursor cells committed to the myeloid cell-line differentiation. "In cancers of the blood system, MRPL33 affects the receptor tyrosine kinase TrkA or KIT expression levels in acute myeloid leukemia (AML) and neuroblastoma, which has a prognostic value for both types of cancer." (PMID 33238645, 2020).
autism spectrum disorder (1 paper, 2023). A spectrum of developmental disorders that includes autism, and Asperger syndrome. "MRPL33 has been causally associated with a higher risk of autism spectrum disorder and with angiotensin-converting enzyme 2 and testosterone levels." (PMID 36984843, 2023). "The functions of MRPL33 and C2orf16 as solute carriers are not entirely known, but they have been reported to involve neuroendocrine diseases, such as autism spectrum disorder and type 2 diabetes." (PMID 36984843, 2023).
bladder urothelial carcinoma (1 paper, 2023). "Additionally, GNLY, HOXB7, MRPL33, and PRDM16 were upregulated in bladder urothelial carcinoma, colon adenocarcinoma, lung adenocarcinoma, and rectum adenocarcinoma based on the results of eRic validation." (PMID 37534217, 2023).
breast carcinoma (1 paper, 2020). "MRPL33, a protein in mt-LSU, is linked with breast cancer metastasis through RNA depth sequencing (RNA-seq) analysis and the content of MRPL33 exon 3 was significantly increased in breast cancer, lung cancer, colon cancer, etc.." (PMID 33238645, 2020).
colitis (1 paper, 2021). Inflammation of the colon. "In addition, a genome-wide comparison of gene expression in genetically susceptible animals that develop spontaneous colitis showed that despite most upregulated genes in experimental colitis are immune-related, AQP4 and the mitochondrial ribosomal protein L33 were also strongly upregulated." (PMID 33673336, 2021).
congenital hypothyroidism (1 paper, 2025). A thyroid hormone deficiency present from birth. "APP, DDB1, MRPS5, and MRPL33 are hub genes with low expression levels in congenital hypothyroidism (CH)." (PMID 41169358, 2025).
diabetes (1 paper, 2017). "Besides confirming functional relevance of previously reported candidate genes with diabetes, SMR analysis also identified several novel candidate genes for diabetes, such as MRPL33, ACP2, and NR1H3." (PMID 28744461, 2017).
gastric cancer (1 paper, 2025). A primary or metastatic malignant neoplasm involving the stomach. "A recent study has shown that RBM39 regulated cell proliferation by affecting the splicing of MRPL33 in gastric cancer cells." (PMID 40223119, 2025).
neuroendocrine disorder (1 paper, 2023). A disease or disorder that affects the neuroendocrine gland, any of the organized aggregations of cells that function as secretory or excretory organs and that release hormones in response to neural stimuli. "Overall, the causal effect may involve two pathophysiological pathways, including glucose metabolism (PPM1K and TRMT61A) related to plaque progression and the newly discovered neuroendocrine disorders (CBLN1, MRPL33, and C2orf16) related to plaque rupture and thrombosis." (PMID 36984843, 2023).
Obesity (1 paper, 2012). Accumulation of substantial excess body fat. "Navigating syntenic regions suggests obesity candidate genes on chromosome 2 that are previously known to be associated with obesity-related diseases: MRPL33, PARD3B, ERBB4, STK39, and ZNF385B." (PMID 23253381, 2012).
cancer (5 papers, 2019 to 2025). A tumor composed of atypical neoplastic, often pleomorphic cells that invade other tissues. "The MRPL33 gene that encodes large mitoribosomal sub-units regulates growth and apoptosis in cancer and may also be implicated in chemoresistance." (PMID 31681584, 2019). "The depletion of MRPL33’s long isoform (MRPL33-L) which contains exon 3, has been shown to impair proliferation and increase apoptosis in both cancer cell lines and xenograft models." (PMID 37664052, 2023). "The isoform-specific knockdown of exon 3-containing MRPL33 mRNA (MRPL33-L) inhibits cancer cell growth and considerably induces cell death." (PMID 33238645, 2020). "We also report that SLC18A2, PLXNC1, and MRPL33 gene expression is associated with TrkA or KIT expression levels in both AML and NB, and these genes have a prognostic value for both cancers." (PMID 31681584, 2019). "However, the effects of the two MRPL33 isoforms on cancer have not been completely elucidated." (PMID 37534217, 2023).
tumor (4 papers, 2011 to 2025). "MRPL33 is required for mitochondrial function and has been implicated in tumor progression." (PMID 36233293, 2022). "Transcriptional profiles identified 39 genes that differentiated between 19 'metastatic' and 35 'non-metastatic' tumours, with molecular pathways involved in protein translation most strongly represented (MRPL33, RPL12, RPL27A, RPS5, RPS9)." (PMID 21385341, 2011).
MRPL33 also shares sentences with these, for which no sentence is quoted: atherosclerosis (1 paper); colon adenocarcinoma (1); colon cancer (1); Desminopathy (1); lung adenocarcinoma (1); lung carcinoma (1); rectum adenocarcinoma (1); type 2 diabetes (1).